LCAT (lecithin-cholesterol acyltransferase)
Diseases named in the same sentence as LCAT in open-access papers (continued):
Sharing a sentence is not in itself a finding about the gene and the disease.
peritonitis (1 paper, 2021). Inflammation of the peritoneum (tissue that lines the abdominal wall and covers most of the organs in the abdomen). "Importantly, PSM-induced peritonitis in LCAT−/− mice resulted in increased lysis of resident peritoneal macrophages and enhanced neutrophil recruitment into the peritoneal cavity." (PMID 34321507, 2021).
preeclampsia (1 paper, 2023). Preeclampsia is a hypertensive disorder of pregnancy that is characterized by new-onset hypertension with proteinuria presenting after 20 weeks of gestation, and depending on mild or severe forms may initially present with severe headache, visual disturbances, and hyperreflexia. "On the other hand, our results showed no significant change in LCAT activity during pregnancy in women with preeclampsia, i.e., there was an absence of a typical answer of LCAT to a rise in cholesterol levels between trimesters in PG." (PMID 37511116, 2023). "Reduced capacity for intestinal HDL synthesis, decreased LCAT activity, and impaired capacity for HDL-mediated cholesterol efflux could be the contributing mechanisms resulting in lower HDL cholesterol levels prior to late-onset preeclampsia, while CETP involvement seems to be of lesser importance." (PMID 37511116, 2023).
primary biliary cholangitis (1 paper, 2020). Primary biliary cholangitis (PBC) is a chronic and slowly progressive cholestatic liver disease of autoimmune etiology characterized by injury of the intrahepatic bile ducts that may eventually lead to liver failure. "LP-X concentrations are increased in subjects with lecithin-cholesterol acyltransferase (LCAT) deficiency and primary biliary cholangitis (PBC)." (PMID 32927635, 2020).
prion disease (1 paper, 2014). A transmissible disease that is caused by a protein that is able to induce abnormal folding of normal cellular proteins, leading to characteristic spongiform brain changes, which are associated with neuronal loss without an inflammatory response. "Since APOC1 is able to activate cholesterol esterification via lecithin-cholesterol acyltransferase, its up-regulation could lead to an increase in cholesterol biosynthesis, consistent with the concomitant presence of prion disease." (PMID 24898206, 2014).
Schistosoma haematobium infection (1 paper, 2025). "Machine learning emphasized SYNPO2, CD276, α2M, LCAT, and hnRNPM as the most discriminating biomarkers for Schistosoma haematobium infection." (PMID 40853910, 2025). "This aligns with our findings in Schistosoma haematobium infection, where LCAT dysregulation may contribute to lipid metabolism abnormalities and inflammatory responses, ultimately supporting parasite survival." (PMID 40853910, 2025).
steatosis (1 paper, 2025). Increased lipid within the cytoplasm of cells. "At the end of the HFHC diet feeding period, histological examinations of liver tissue revealed severe steatosis and ballooning degeneration in LCAT KO hamsters." (PMID 41195480, 2025).
uremia (1 paper, 2015). A clinical syndrome associated with the retention of renal waste products or uremic toxins in the blood. "For example, patients with high atherosclerotic vascular disease risks, such as smokers, exhibit lower HDL PON-1 mass and activity than those with low risks, such as nonsmokers; moreover, uremia patients have lower LCAT levels and activities than patients without uremia." (PMID 26090384, 2015).
uterine corpus endometrial carcinoma (1 paper, 2025). A endometrial carcinoma (disease) that involves the body of uterus. "In kidney renal papillary cell carcinoma (KIRP) and uterine corpus endometrial carcinoma (UCEC), LCAT CNV and methylation levels are prognostic markers." (PMID 40003919, 2025).
uveitis (1 paper, 2025). An inflammatory process affecting a part of or the entire uvea. "Another important differential is a lipid or crystalline pseudohypopyon, which may occur in metabolic disorders such as lecithin-cholesterol acyltransferase (LCAT) deficiency, longstanding uveitis, or degenerative ocular conditions." (PMID 41466893, 2025).
cardiovascular disease (26 papers, 2013 to 2025). "LCAT-targeted therapies have emerged as a promising approach for treating LCAT deficiency and potentially other cardiovascular diseases." (PMID 39244794, 2024). "Although glycation modification of LCAT has not been reported before, other modifications, such as glycosylation, have been found to influence LCAT function and are associated with cardiovascular disease, an age-related condition." (PMID 37654074, 2023). "Previous studies have linked LCAT activity to atherosclerotic cardiovascular disease risk, and altered function due to gene mutations has been associated with atherosclerotic pathology." (PMID 37654074, 2023). "Overall, the results, mechanisticinsights, and methodology reported here will provide a blueprint thatcan be utilized to design novel drug formulations against LCAT deficienciesand cardiovascular diseases in the future." (PMID 36111986, 2022). "Positive allosteric modulators have been developed to treat LCAT deficiencies and, plausibly, also cardiovascular diseases in the future." (PMID 33720934, 2021). "We described three patients with mutations in CETP, LCAT, and ABCA1, demonstrating the clinical presentation and risk for cardiovascular disease." (PMID 40476138, 2025). "Current researches were predominantly focused on elucidating the role of LCAT in the pathogenesis and therapeutic modulation of cardiovascular diseases." (PMID 40927188, 2025). "Sex-specific differences in LCAT activity have been previously documented in individuals with cardiovascular disease, and observations in the present study are now extend this to severe AS." (PMID 35643498, 2022). "LCAT showed a cardiovascular disease preventive effect during physiological states, however, multiple pathological and physio-pathological alterations lead to the change of serum LCAT and the protection diminished subsequently." (PMID 36588724, 2022). "Pearson bivariate correlation between lecithin-cholesterol acyltransferase, paraoxonase-1 and conventional lipid profile of atherosclerotic cardiovascular diseases patients at Lagos State University Teaching Hospital, Lagos, Nigeria, between March 2022 and March 2023." (PMID 39114750, 2024). "Plasma LCAT and PON-1 may serve as independent markers or complement other established cardiovascular disease markers to discriminate the risk of ASCVD when it is unclear." (PMID 39114750, 2024). "Recently, a Phase I clinical trial has shown that recombinant LCAT is safe in patients with stable cardiovascular disease and moreover, the lipid and lipoprotein abnormalities of one patient with FLD was reported to be corrected by treatment with recombinant LCAT." (PMID 26919698, 2016). "Moreover, a separate study indicated that lycopene could prevent cardiovascular disease through improvement of the HDL functionality by stimulating the activity of the lecithin cholesterol acyltransferase (LCAT)." (PMID 32764462, 2020). "Thus, a decrease in LCAT activity in 24-month-old animals may be one of the causes of increased oxidized LDL levels in old age, which in turn, may increase the risk of cardiovascular disease." (PMID 23936611, 2013). "If so, then activation of LCAT by a small molecule approach and improving HDL function could be widely used in the primary prevention of cardiovascular disease and would likely complement our existing drugs for lowering LDL-C, such as statins and PCSK9-inhibitors." (PMID 30479275, 2018).
cancer (23 papers, 2014 to 2025). A tumor composed of atypical neoplastic, often pleomorphic cells that invade other tissues. "In various cancer types, hypermethylation is associated with reduced expression, and LCAT methylation levels significantly impact tumor progression in LGG, LIHC, SARC, and UVM." (PMID 40003919, 2025). "The expression levels of LCAT are closely associated with the prognosis of patients across various cancers, potentially serving as a biomarker for predicting treatment response." (PMID 40003919, 2025). "The impact of genetic and epigenetic variations on LCAT function offers new insights for cancer therapy." (PMID 40003919, 2025). "As a key molecule linking lipid metabolism, immune modulation, and tumor progression, the potential of LCAT in cancer therapy is significant." (PMID 40003919, 2025). "Our findings provide new insights into the role of LCAT in cancer biology and support the development of personalized treatment strategies." (PMID 40003919, 2025). "Lecithin cholesterol acyltransferase (LCAT) is a crucial enzyme in high-density lipoprotein (HDL) metabolism that is often dysregulated in cancers, affecting tumor growth and therapy response." (PMID 40003919, 2025). "In the CTRP database, LCAT mRNA expression is significantly correlated with the IC50 of various anti-cancer drugs." (PMID 40003919, 2025). "The aim of this study is to investigate LCAT expression patterns in different cancer types and their correlation with clinical outcomes, like survival." (PMID 40003919, 2025). "Our comprehensive analysis of the role of LCAT in various cancers reveals its potential as a biomarker and therapeutic target, emphasizing the necessity of understanding its mechanisms of action." (PMID 40003919, 2025). "This study uses systematic approaches to clarify the roles of LCAT in tumor growth in light of the diversity of cancer and the intricacy of lipid metabolic pathways." (PMID 40003919, 2025). "We examined LCAT expression in different cancer types using extensive genomic databases and cutting-edge bioinformatics methods, and we connected the findings to clinical characteristics." (PMID 40003919, 2025). "The interaction between LCAT and m6A regulatory factors provides a new avenue for understanding post-transcriptional regulatory mechanisms in cancer." (PMID 40003919, 2025). "Although our study provides valuable insights into the role of LCAT in cancer, the mechanism by which LCAT has a dual nature in different cancer types requires further investigation." (PMID 40003919, 2025). "The role of LCAT in regulating immune responses in the tumor microenvironment and drug sensitivity underscores its potential in cancer treatment." (PMID 40003919, 2025). "The role of LCAT in cancer biology is complex and context-dependent, reflecting its dual nature as both a tumor suppressor and a potential promoter of tumor progression." (PMID 40003919, 2025). "The CNV pie chart shows the composition of the heterozygous/homozygous CNVs of the LCAT gene in 33 cancers." (PMID 40003919, 2025). "Our knowledge of the function of LCAT in cancer is severely constrained by the paucity of thorough studies on LCAT expression and activity across different tumor types." (PMID 40003919, 2025). "The goal of this research is to present a thorough analysis of the participation of LCAT in cancer while also shedding light on its therapeutic relevance and mechanisms of action." (PMID 40003919, 2025). "This study unveils the multifaceted roles of LCAT in cancer, particularly its key involvement in tumor immune modulation and progression." (PMID 40003919, 2025). "Our research findings indicate that ADH4 and LCAT are genes that undergo significant changes during the differentiation of hepatocytes into cancer cells." (PMID 38654290, 2024). "In this study, we also explored the potential roles of CD5L, LCAT, and CDC20 in HCC therapy and found their associations with anti-cancer drug sensitivities in HCC cell lines." (PMID 36494696, 2022).
cancer (continued). "Our functional enrichment analysis revealed that LCAT inhibits tumor progression in these cancers through pathways such as complement and coagulation cascades and oxidoreductase activity, which are critical for maintaining cellular homeostasis and suppressing tumorigenesis." (PMID 40003919, 2025). "Additionally, we examined the genetic and epigenetic modifications of LCAT in cancer and their impact on the biological properties of tumors." (PMID 40003919, 2025). "Recent research has begun to shed light on the role of LCAT in cancer biology, with findings indicating that LCAT activity may be disrupted in a variety of malignant tumors, potentially affecting tumor progression and response to therapy." (PMID 40003919, 2025). "However, the exact mechanisms by which LCAT contributes to carcinogenesis, as well as its clinical significance across various cancer types, have yet to be fully understood." (PMID 40003919, 2025). "Furthermore, we analyzed the correlation between LCAT expression and TMB as well as MSI in different tumors and found that LCAT expression is significantly associated with the levels of TMB and MSI across various cancers." (PMID 40003919, 2025). "Our immunological analysis suggests that high LCAT expression is associated with a reduction in immune cell infiltration in several cancers, indicating that LCAT may contribute to immune evasion mechanisms." (PMID 40003919, 2025). "It is worth further exploring whether the T stage and new cancer events were reversed by regulating LCAT and RPS6KA6." (PMID 34034705, 2021). "LCAT expression and activity regulation could be a new cancer therapy target." (PMID 40003919, 2025). "Additionally, the interaction between cytokines and cytokine receptors may be regulated by LCAT in both cancers, explaining the common mechanism of action of LCAT in different cancers." (PMID 40003919, 2025). "Interestingly in the current study, we observed that LCAT gene could classify cancer and normal samples with AUC 0.92, is also identified as one of the important markers (LS-RNA-WEKA) to distinguish early stage samples from the late stage." (PMID 31490960, 2019). "We used the “GDSC” and “CTRP” modules of the GSCA online tool to analyze the correlation between LCAT expression and the IC50 of various anti-cancer drugs." (PMID 40003919, 2025). "Understanding the tricky relationship between LCAT, lipid metabolism, and most cancers’ progression is fundamental for the improvement of centered treatments and might also pave the way for customized therapy techniques that harness the doable of modulating LCAT recreation in most cancer treatments." (PMID 40003919, 2025). "They identified 54 proteins that were higher in cancer than in normal plasma, including SERPING1, SERPINA6, and lecithin cholesterol acyltransferase (LCAT)." (PMID 37893211, 2023). "CD5L, LCAT and CDC20 were shown to be significantly correlated with immune/stroma cell infiltrations, immunoregulators and 31 anti-cancer drug sensitivities in HCC." (PMID 36494696, 2022). "GREAT also reported that HepG2-enriched windows were close to many cancer genes HPX, HPN, LCAT, TST, GSTM1, CEPBA, CYP2B6." (PMID 25522020, 2014). "The role of LCAT in the maturation of HDL and the conversion of free cholesterol into cholesterol ester may affect the cholesterol content and homeostasis in cancer cells." (PMID 40003919, 2025). "LCAT has been reported as a prognostic and recurrence biomarker in HCC and has been correlated to anti-cancer drug sensitivities." (PMID 38689649, 2024). "The results revealed a significantly lower expression of LCAT in cancer tissues than in adjacent nontumor tissues." (PMID 38195525, 2024). "In the GDSC and CTRP databases, LCAT expression was significantly correlated with the IC50 of various chemotherapeutic drugs, suggesting that LCAT may influence drug resistance or sensitivity in cancer cells." (PMID 40003919, 2025).
tumor (21 papers, 2015 to 2025). "Pseudotime analysis of gene expression in the risk model revealed that the expression levels of FTCD and LCAT, associated with good prognosis, were higher in the late stages of tumor development." (PMID 39132167, 2024). "The tumor diagnostic model was formulated as follows: logit (P-HCC) = 6.906 - 0.494 * SOCS2 expression level - 1.250 * LCAT expression level – 0.493 * FTCD expression level + 0.602 * KRT17 expression level + 1.950 * PBK expression level + 7.243 * CBX2 expression level." (PMID 36159831, 2022). "The tumor diagnostic model was formulated as follows: logit (P-HCC) = -2.534 – 1.240 * SOCS2 expression level - 1.320 * LCAT expression level + 0.335 * FTCD expression level – 1.911 * KRT17 expression level + 4.422 * PBK expression level + 2.006 * CBX2 expression level." (PMID 36159831, 2022). "The expression of LCAT in tumor cell lines and the website-based predictions of its subcellular localization both indicate significant nuclear expression of LCAT." (PMID 40003919, 2025). "Differential expression analysis of LCAT between tumor tissues and paired normal tissues yielded similar results." (PMID 40003919, 2025). "Our findings highlight the importance of understanding the multifaceted roles of LCAT in tumor biology, particularly its involvement in lipid metabolism, immune modulation, and epigenetic regulation." (PMID 40003919, 2025). "For instance, in LGG and LIHC, LCAT likely exerts its tumor-suppressive effects by regulating lipid metabolism and immune responses." (PMID 40003919, 2025). "The Reactome enrichment analysis results show that LCAT is most likely to promote ACC tumor progression through collagen degradation; LCAT is most likely to promote COAD tumor progression by affecting cornified envelope formation." (PMID 40003919, 2025). "LCAT is most likely to inhibit LGG tumor progression by affecting peptide chain elongation; LCAT is most likely to inhibit LIHC tumor progression through complement cascades." (PMID 40003919, 2025). "The KEGG enrichment analysis results indicate that LCAT is most likely to promote ACC tumor progression through the IL-17 signaling pathway; LCAT is most likely to promote COAD tumor progression through complement and coagulation cascades." (PMID 40003919, 2025). "We also examined the copy number variations (CNVs), single-nucleotide variations (SNVs), DNA methylation, and N6-methyladenosine (m6A) modifications of LCAT and their connections to tumor immune responses and drug sensitivity." (PMID 40003919, 2025). "LCAT is most likely to inhibit LGG tumor progression by affecting focal adhesion formation; LCAT is most likely to inhibit LIHC tumor progression through glycine, serine, and threonine metabolism." (PMID 40003919, 2025). "The correlation between CNVs and LCAT expression underscores the necessity of understanding how genomic alterations lead to the dysregulation of metabolic enzymes in the tumor environment." (PMID 40003919, 2025). "Future studies should also explore the interactions between LCAT and other metabolic enzymes in the tumor microenvironment, as well as the role of LCAT in regulating immune cell function and immunotherapy response." (PMID 40003919, 2025). "In LGG and LIHC tumors, LCAT is likely to inhibit tumor progression through complement and coagulation cascades." (PMID 40003919, 2025). "The study found a significant decrease in LCAT expression in tumor tissue compared to non-tumor tissue, as confirmed by immunohistochemical analysis in HCC." (PMID 38654290, 2024). "Since LCAT is a newly discovered tumor suppressor, it is worthwhile to further investigate the molecular mechanisms by which LCAT affects disulfidptosis in HCC." (PMID 38195525, 2024). "Lysophosphatidylcholine (LysoPC) is produced from phospholipids through the action of phospholipase A2 (LPA2) or lecithin cholesterol acyltransferase (LCAT) and plays a key role in regulating cell proliferation, tumor infiltration, and inflammation." (PMID 39590846, 2024).